RNU6-582P (RNA, U6 small nuclear 582, pseudogene)
Gene: Small nuclear RNA gene on chromosome 4 (157,201,562 to 157,201,668, reverse strand). Ensembl gene ENSG00000199859.
Homologues: Orthologues: chimpanzee U6 (95% identical), macaque U6 (84% identical). Paralogues in human: RNU6-25P (90% identical), RNU6-1 (89% identical), RNU6-2 (89% identical), RNU6-29P (89% identical), RNU6-39P (89% identical), RNU6-3P (89% identical), RNU6-45P (89% identical), RNU6-48P (89% identical), RNU6-4P (89% identical), RNU6-5P (89% identical), RNU6-6P (89% identical), RNU6-9 (89% identical), and 1287 more.